EGFR (epidermal growth factor receptor)
Diseases named in the same sentence as EGFR in open-access papers (continued):
Sharing a sentence is not in itself a finding about the gene and the disease.
lung cancer (continued). "The identification of EGFR mutations in lung cancer has led to an explosion of interest in studying the mechanisms underlying lung cancer pathogenesis, focusing on the role of HER family proteins." (PMID 17667926, 2007). "The development of the EGFR T790M mutation in lung cancers confers drug resistance and is associated with persistent activation of HER3/PI3K/Akt signalling." (PMID 17667926, 2007). "A similar clinical benefit is observed in patients with lung cancers harboring the two most common EGFR activating mutations, L858R and exon 19 deletions." (PMID 17973572, 2007). "An obvious explanation would be that these cells express activating mutations in EGFR that would make them sensitive to Iressa, as has been described for lung cancer." (PMID 17875215, 2007). "As many genes are mutated in lung carcinomas (K-Ras, EGFR for example), mutational analysis of RhoB sequence has been performed by several teams in various tumors and were all negative." (PMID 18047684, 2007). "Some non-small cell lung cancers (NSCLC, the commonest type of lung cancer), for example, have activating mutations within the EGFR tyrosine kinase." (PMID 17973573, 2007). "Somatically acquired mutations in the epidermal growth factor receptor (EGFR) gene in lung cancer are associated with significant clinical responses to gefitinib, a tyrosine kinase inhibitor that targets EGFR." (PMID 16552419, 2006). "In this study, we analysed the EGFR mutations in exons 19 and 21 by simple screening methods based on PCR in a large scale of Japanese patients with lung cancer, and investigated the clinical significance of these mutations." (PMID 16552419, 2006). "Although a low expose of smoking reduces the risk for lung cancer, EGFR mutations are suggested to be related to the occurrence of lung adenocarcinoma in nonsmoker." (PMID 16552419, 2006). "Peptide nucleic acid-locked nucleic acid PCR clamp can rapidly (within 2 hours) detect EGFR mutations from all specimens used to diagnose lung cancers, that is, sputum, pleural effusion and bronchial washing which contain many normal cells." (PMID 17106442, 2006). "EGFR activating mutations have been described in lung cancer and in brain tumours, but these mutations have proven extremely rare in other types of cancer, including breast carcinomas." (PMID 16280056, 2005). "Organ-specific differences in epidermal growth factor receptor (EGFR) mutational spectra and frequencies were found in lung cancer and sporadic and BRCA1/2-related breast cancers." (PMID 15841079, 2005). "High expression of EGFR has been reported in various epithelial malignant tumours, including lung cancer, and has been shown to play a causal role in disease progression." (PMID 15870831, 2005). "Epidermal growth factor receptor (EGFR) mutations are a potential predictor of the effectiveness of EGFR inhibitors for the treatment of lung cancer." (PMID 16052218, 2005). "It has been shown that the presence of somatic mutations in the EGFR gene in lung cancer samples correlates with sensitivity to gefitinib." (PMID 15987464, 2005). "In GISTs (KIT and PDGFRA mutations), breast carcinoma (HER-2 amplification) and lung cancer (EGFR mutation), targeted therapy has yielded best results in cases with activating mutation or amplification of the respective gene." (PMID 15583695, 2004). "Lung cancers harbouring epidermal growth factor receptor mutations are characterized by treatment options that are better in terms of efficacy and quality of life compared with the majority of different types of lung cancers." (PMID 41590374, 2026). "In this study, three point mutations of EGFR relevant to lung cancer therapy are detected." (PMID 41595675, 2026).
lung cancer (continued). "In addition to the definitive lung cancer-associated T790M mutation in the EGFR gene, new drug-resistant mutations such as C797S can lead to the failure of existing targeted drugs." (PMID 41472727, 2025). "This represented a novel mechanism underlying EGFR-TKIs resistance in lung cancer." (PMID 39744423, 2025). "Rare EGFR mutations could also be equally important targets in the treatment of advanced-stage lung cancer; therefore, detailed information regarding EGFR mutation type is needed to apply appropriate therapies." (PMID 40591555, 2025). "Epidermal growth factor receptor (EGFR) mutations represent one of the most common actionable oncogenic drivers in non–small cell lung cancer (NSCLC), affecting approximately 10-15% of patients with advanced disease in Western countries and up to 40–50% in Asia." (PMID 41438982, 2025). "In contrast, small-molecule targeted therapies, especially those targeting EGFR, showed higher specificity and sensitivity in EGFR-mutated lung cancer cell lines cultured in the 3D system, suggesting altered receptor expression and signaling compared to 2D models." (PMID 41050078, 2025). "Furthermore, elevated HER3 levels have been observed in EGFR-mutated lung cancer models following osimertinib treatment." (PMID 40243603, 2025). "Likewise, ACT therapies, including TILs, CAR-T cells, and CAR-NK cells, have shown encouraging activity in targeting lung cancer-associated antigens such as EGFR, MUC1, and mesothelin." (PMID 41394845, 2025). "In addition, DUSP6 was reported to be upregulated in early lung cancer lesions with activating EGFR or RAS mutations." (PMID 41210685, 2025). "In addition, GLS1 expression was positively correlated with EGFR expression, particularly within the cohort of EGFR‐mutated lung cancer patients." (PMID 39680480, 2025). "Also, our study found that ACACA mRNA expression is significantly higher in lung cancer patients with EGFR mutations than those with wild-type EGFR." (PMID 41169354, 2025). "EGFR-TKIs have demonstrated efficacy in treating lung cancer patients with EGFR mutations." (PMID 39744423, 2025). "Additionally, miR-155 is essential in resistance to targeted therapies, such as the EGFR tyrosine kinase inhibitor (TKI) gefitinib, used to treat lung cancers with activating EGFR mutations." (PMID 39963112, 2025). "Studies on prediction of EGFR mutation in lung cancer based on deep learning methods." (PMID 40708937, 2025). "Building on this foundation, we hypothesize that RBM10 influences BBB permeability in EGFR-mutated lung cancer by regulating sphingolipid metabolism." (PMID 40069781, 2025). "However, among the immune‐chemotherapy options, ABCP showed relatively favorable outcomes in EGFR mutation‐positive lung cancer." (PMID 40961974, 2025). "Lung cancer patients with EGFR mutations have high prevalence of brain metastases." (PMID 40696624, 2025). "However, the mutation rate of the EGFR lung cancer patients in Europe and America is only approximately 15%." (PMID 39907159, 2025).
lung cancer (continued). "This study is the first to report the significant cytotoxic effect of panduratin A on the H1975 lung cancer cell line, an established model bearing the T790M mutation in addition to the L858R mutation, which is commonly used to study acquired resistance to EGFR-TKIs." (PMID 40076971, 2025). "Moreover, FOXM1 and ASCL1, which is not regard as classical EMT‐TFs, is demonstrated to induce EMT‐associated EGFR TKI resistance in lung cancer." (PMID 41415713, 2025). "Whether immune checkpoint inhibitors (ICI)—a promising therapeutic approach in lung cancer —confer survival benefits in patients with uncommon EGFR mutations or 20ins remained unclear and warranted further investigation." (PMID 41162774, 2025). "Biological factors, such as hormonal differences and genetic factors (e.g., higher prevalence of EGFR mutations in women), may also influence the susceptibility of women to lung cancer development." (PMID 39916713, 2025). "Epidermal growth factor receptor (EGFR), a cell surface protein, is mutated in many lung cancers." (PMID 40940888, 2025). "Furthermore, this review highlights the necessity of prospective, multicentre study to determine the pattern of EGFR-mutated lung cancer and how it adheres to existing treatments in order to develop a suitable strategy for the South Asian population." (PMID 41333366, 2025). "Specifically, EGFR driver mutations, such as L858R (LR) and deletions in exon 19 (ex19del), are commonly found in non‐small cell lung cancer (NSCLC), and tumors harboring these mutations are especially responsive to treatment with small‐molecule tyrosine kinase inhibitors (TKIs)." (PMID 40665765, 2025). "EGFR gene polymorphism in Chinese patients with lung cancer." (PMID 40438325, 2025). "The search strategy combined controlled vocabulary (e.g., MeSH) and free‐text terms, including “EGFR,” “epidermal growth factor receptor,” “mutation,” “deep learning,” “artificial intelligence,” “radiomics,” “machine learning,” and “non‐small cell lung cancer,” with Boolean operators." (PMID 40708937, 2025). "MDM2 amplification is also associated with TKI resistance, particularly in lung cancer, where its inhibition has been explored as a means to overcome resistance to epidermal growth factor receptor (EGFR)-targeted therapies and BCR-ABL1 inhibitors in chronic myeloid leukemia." (PMID 41170373, 2025). "Among these, EGFR is the most frequently targeted mutation in lung cancer therapy." (PMID 41282618, 2025). "Furthermore, the S303F mutation, together with a previously identified activating ERBB4 mutation, E715K, promoted resistance to third-generation EGFR inhibitor osimertinib in EGFR-mutant lung cancer model in vitro and in vivo." (PMID 41437739, 2025). "Given the prevalence of EGFR mutations in adenocarcinoma among East Asian females who are never-smokers, it is hypothesized that higher parity might inversely affect lung cancer risk by inhibiting EGFR activation or mutation." (PMID 40831928, 2025). "However, when the C797S and T790M mutations are trans (located in distinct alleles), lung cancer cells have been demonstrated to respond well to the combined therapy of first- and third-generation EGFR-TKIs." (PMID 40361442, 2025). "PCs exhibit a unique secretome, with high secretion of IL-32, in EGFR mutated lung cancer patients." (PMID 40248695, 2025). "However, data on early‐stage EGFR‐mutated lung cancer, particularly large‐scale epidemiologic studies, are relatively scares in Korea." (PMID 39757012, 2025). "We hypothesize that analgesic use is associated with time on treatment and survival in EGFR TKI‐treated lung cancer patients." (PMID 40650440, 2025). "EGFR mutations were exclusively detected in lung cancer patients (19.5%)." (PMID 39748775, 2025). "Additionally, CDx is commonly performed, especially in lung cancer, and EGFR is the most prevalent driver mutation in lung cancer in Asia, including Japan." (PMID 40616301, 2025).
lung cancer (continued). "In addition, different mutations in the same gene are not always effectively inhibited by the same targeted therapy, as has been observed in gastrointestinal stromal tumors with KIT mutations and in lung cancer with EGFR mutations." (PMID 39941744, 2025). "Potential upstream activators of STAT3 in lung cancer include IL-6, which has been reported to be constitutively produced in some lung cancer cell lines and lung cancer patients, and EGFR, which is often overexpressed or mutated in the kinase domain in NSCLC cells." (PMID 41380973, 2025). "The YAP/FOXM1 axis contributes to EGFR inhibitor resistance associated with EMT in lung cancer." (PMID 40066231, 2025). "Consequently, the identification of key genes associated with stemness-phenotype in EGFR-TKIs-resistant lung cancer cells holds promise for overcoming resistance and improving outcomes for these patients." (PMID 39744423, 2025). "For early-resected lung cancers with EGFR mutations, adjuvant EGFR TKIs could be prioritized for patients with a low TLS density in the tumor microenvironment." (PMID 40723259, 2025). "Among these, the epidermal growth factor receptor (EGFR) is the most extensively studied biomarker in lung cancer, encompassing multiple mutations that assist clinicians in optimizing therapeutic decisions, including the initiation or discontinuation of targeted treatments." (PMID 41373464, 2025). "For example, whether targeted therapy can be integrated into the regimen for MPMNs with actionable mutations (e.g., EGFR mutations in lung cancer, BRCA mutations in ovarian cancer) requires further investigation." (PMID 41584613, 2025). "Such scenarios relate to biomarkers and testing in lung cancer, small cell lung cancer, EGFR mutations and targeted therapy in non-small cell lung cancer (NSCLC), early-stage NSCLC, KRAS/BRAF/MET and other genomic alterations in NSCLC, and immunotherapy in advanced NSCLC." (PMID 39237103, 2025). "PM2.5 exposure is also linked to increased lung cancer incidence driven by EGFR and KRAS mutations." (PMID 39578555, 2025). "The EGFR-TKIs (epidermal growth factor receptor-tyrosine kinases inhibitors) offer significant benefits to lung cancer patients with sensitive EGFR mutations; however, the development of acquired resistance poses a significant challenge and leads to poor prognosis." (PMID 39744423, 2025). "Genomic studies have identified driver mutations associated with primary lung cancer, including epidermal growth factor receptor (EGFR), anaplastic lymphoma kinase (ALK), ROS1 Proto-Oncogene Tyrosine Kinase Receptor (ROS1) and Serine/Threonine-Protein Kinase BRAF (BRAF)." (PMID 40492223, 2025). "This agrin‐EGFR‐integrin‐YAP/TAZ‐agrin positive cycle may be of great relevance for the stiff lung cancer matrix in patients harboring EGFR mutations." (PMID 40165020, 2025). "EGFR‐targeted therapy is highly effective for multiple cancer types, including non‐small cell lung cancer, head and neck cancer, and colorectal cancer, particularly when they have EGFR genomic changes such as specific somatic mutations, gene amplification, or EGFR protein overexpression." (PMID 39129344, 2025). "Moreover, as EGFR hotspot driver mutations are biomarkers in cancer treatment and are routinely tested in lung cancer samples, we compared our results with those of previous clinical tests performed on the same samples." (PMID 40867048, 2025). "For instance, the early detection of EGFR mutations can prompt the initiation of targeted therapy with third-generation tyrosine kinase inhibitors, such as Osimertinib, thereby significantly improving the survival rate of lung cancer patients." (PMID 40949724, 2025).
lung cancer (continued). "This case highlights the potential efficacy of combining anti-angiogenic agents with targeted therapies like EGFR TKIs in EGFR-mutated advanced lung cancer, as evidenced by the remarkable tumor cavitation observed with the aumolertinib and anlotinib combination." (PMID 40428273, 2025). "However, a growing body of evidence suggests that WT-EGFR is critical in lung cancer progression, linked to third-generation EGFR-TKI resistance and KRAS-driven NSCLC maintenance." (PMID 40533443, 2025). "Genes associated with EGFR mutations in lung cancer samples were analyzed using TCGA." (PMID 40124619, 2025). "Awareness of this rare recurrence pattern is essential, as prolonged survival of patients with EGFR-mutated lung cancer may increase the likelihood of encountering such atypical metastatic phenomena." (PMID 41416296, 2025). "In this regard, a recent case report shows that a patient with EGFR-mutated lung cancer who developed resistance to osimertinib and expressed exon 20 insertion mutation in HER2 gained approximately 8 months of benefit from the combination of the third-generation EGFR TKI and trastuzumab deruxtecan." (PMID 40243603, 2025). "Here, we present the initial instance of a non‐small cell lung cancer (NSCLC) patient with an EGFR mutation who also harbored both NTRK1 and ZRSR2 mutations, which are recognized as significant factors in the development of primary resistance to Osimertinib through further validation." (PMID 39907312, 2025). "Hypertriglyceridemia was associated with lower risks of lung cancer (0.93 [0.89–0.98], p = 0.0005), lung adenocarcinoma (0.90 [0.84–0.96], p = 0.0006) and EGFR-mutated lung cancer (0.97 [0.78–0.96], p = 0.0082) as well as a greater risk of small-cell lung cancer (1.31 [1.11–1.55], p = 0.0018)." (PMID 39883280, 2025). "The identification of activating EGFR mutations, along with the associated increased sensitivity to EGFR TKIs, represents a critical initial step in the implementation of targeted treatment strategies for lung cancer." (PMID 41153394, 2025). "While current EGFR mutation detection kits demonstrate high sensitivity, directly isolating circulating tumor DNA from the peripheral blood of patients with lung cancer could further improve the detection accuracy and specificity." (PMID 41156384, 2025). "Overall, the molecular docking analysis indicated strong binding affinities between MA and several key proteins associated with lung cancer, including EGFR, MDM2, IGF1R, EZH2, and GSK3B, with binding energies below −10.0 kJ/mol, suggesting exceptional binding strength." (PMID 40070571, 2025). "A recent study demonstrated that neoadjuvant immunochemotherapy in early‐stage lung cancer with EGFR mutations resulted in a major pathological remission rate of 44%, significantly surpassing the efficacy observed in historical controls treated with EGFR‐TKIs." (PMID 39994841, 2025). "For example, PDOs can predict which drug combinations may be effective against genetic mutations (e.g., EGFR mutations in lung cancer) or resistance pathways (e.g., upregulation of ABC transporters)." (PMID 41050078, 2025). "Approximately 15–25% of Caucasians and 40–55% of East Asian patients with lung cancer carry EGFR mutations, and the evolution of tyrosine kinase inhibitors (TKIs) targeting EGFR mutations has improved progression-free survival (PFS) and overall survival (OS) in these patients." (PMID 41228367, 2025). "Similarly, the predominance of classical activating EGFR mutations in lung cancer highlights the role of tissue-specific molecular aberrations in dictating therapeutic responses." (PMID 40576713, 2025).